GATA3 (GATA binding protein 3)
Diseases named in the same sentence as GATA3 in open-access papers (continued):
Sharing a sentence is not in itself a finding about the gene and the disease.
breast carcinoma (continued). "Immunohistochemical staining confirmed the tumor’s origin, with neoplastic cells demonstrating strong nuclear positivity for GATA3, a marker frequently expressed in breast carcinomas." (PMID 41515566, 2025). "Cell type-specific activity estimates (M2Kb and ChIP-Atlas) showed heightened GATA3 activity in luminal A breast cancer, in contrast to reduced activity in basal type, aligning with its known role in promoting luminal activity and cell differentiation." (PMID 39781510, 2025). "The characteristic immunophenotypic profile of CK7+/CK20- combined with GATA3+/CDX2- or GATA3+/SATB2- patterns provides definitive evidence supporting metastatic breast carcinoma to gastrointestinal sites." (PMID 40313249, 2025). "We have shown that the downregulation of GATA3 in breast cancer can be controlled by an aberrant activation of DNMT3B, which induces aberrant methylation in the promoter region of GATA3, in the absence of deleterious somatic alterations." (PMID 40585280, 2025). "Conversely, in breast cancer, BRCA1 depletion was shown to induce hypermethylation of the GATA3 promoter, resulting in transcriptional silencing and loss of epithelial characteristics." (PMID 41514651, 2025). "GATA3 expression occurs in 49%–100% of pT2-4 urothelial carcinomas but is also seen in 42%–100% of breast cancers, in salivary gland neoplasms and–less commonly—also in various other tumor types." (PMID 37777995, 2024). "While previous studies exploring the role of GATA3/FOXA1 focused mostly on breast cancer, there were limited studies on urothelial carcinoma, especially UTUC." (PMID 38425344, 2024). "Data presented herein support the concept that androgen-induced AR/GATA3 interactions facilitate the tumor suppressive function of AR in ER+ and ER- breast cancer contexts." (PMID 38317241, 2024). "GATA3’s involvement in amino acid metabolism regulation is supported by studies in breast cancer, where Glutaminase 2 (GLS2), transcriptionally regulated by the estrogen receptor co-factor GATA3, is more common in hormone receptor-positive tumors." (PMID 39822378, 2024). "Expression of GATA3 is a key feature of luminal breast cancers, whereas the GATA3 gene is often silenced by DNA methylation and its expression is barely detectable in BLBCs." (PMID 38627785, 2024). "Menin is present at enhancers bound by FOXA1 and GATA3, and menin increases the transcription of multiple genes regulated by these enhancers in ER-positive luminal breast cancer cell lines." (PMID 39336822, 2024). "We propose that AR/GATA3-mediated induction of KDM4B facilitates maintenance of a luminal epithelial transcriptome in breast cancer cells and forms part of a tumor suppressive nexus regardless of ER status." (PMID 38317241, 2024). "ZNF503 inhibits GATA3 expression, a key regulator of mammary LEP differentiation, and its downregulation is associated with aggressive breast cancers." (PMID 39545637, 2024). "GATA3 is one of the most widely used markers for breast carcinoma, with a high sensitivity and specificity for breast tissue." (PMID 39518009, 2024). "Unsurprisingly, DESeq yielded DE genes previously known to be co-regulated with ER, such as GATA3 and FOXA1, since these genes are associated with the epithelial phenotype in ER-positive breast cancer cells." (PMID 39199676, 2024). "In current studies, GATA binding protein 3 (GATA3), gross cystic disease fluid protein 15, and mammaglobin are commonly used in diagnosing breast cancer, of which GATA3 is mostly used." (PMID 39432619, 2024). "In luminal breast cancer cells, the transcription factor GATA3 activates the expression of glutamine synthase (GLUL) to facilitate glutamine production, thereby reducing the dependence on extracellular glutamine." (PMID 39272886, 2024).
breast carcinoma (continued). "This is in line with previous researches in breast cancer, where GATA3/FOXA1 co-expressed in ER-positive cancers, as well as GATA3 and FOXA1 genes were the most upregulated out of their corresponding transcription factors in BRCA cancer samples." (PMID 38425344, 2024). "GCDFP-15/mammaglobin/GATA3 are also frequently expressed in breast cancer; however, the positive rate differs among studies." (PMID 37934318, 2024). "This study evaluated the expression of miR‐92a‐3p and miR‐1245b‐5p and their potential target gene, GATA3 in patients with breast cancer (BC)." (PMID 38173189, 2024). "Collectively, these data indicate that GATA3 is a critical co-factor for AR action in ER+ and ER- breast cancer and facilitates AR-mediated tumor suppressor activity." (PMID 38317241, 2024). "Specifically, the combined expression patterns of KDM7A-DT, KRT7, and GATA3 emerge as a promising three-gene prognostic signature for breast cancer." (PMID 38756663, 2024). "Expectingly, Lum breast cancer showed a higher percentage of detected estrogen receptor (ER) and GATA3 positive cells (χ2 = 7.5; df=1; p=0.0062 and χ2 = 22.79; df=1; p=1.8e-06, respectively)." (PMID 38711512, 2024). "Due to the critical role of GATA3 in breast development and as a regulator of ER signaling in breast cancer, we chose to further investigate its functional interaction with AR." (PMID 38317241, 2024). "In the context of ER- breast cancer, the expression of AR and its interaction with GATA3 likely promotes a more differentiated luminal phenotype, explaining why AR-ER- breast cancers represent the most aggressive, undifferentiated breast cancer subtype." (PMID 38317241, 2024). "The degree of AR and GATA3 co-occupancy following treatment with DHT was also high in the ER- breast cancer cell lines, representing 80% of GATA3 binding sites in MDA-MB-453 and 60% in MFM-223 cells." (PMID 38317241, 2024). "Depletion of Gata3, like that of Brca1, promoted DNA damage accumulation in breast cancer cells in vitro and in basal-like breast cancers in vivo." (PMID 38627785, 2024). "This suggests that GATA3 plays a role in tumorigenesis and breast cancer initiation by influencing the differentiation of both epithelial and non-epithelial tissues." (PMID 39768217, 2024). "Men with ER-positive/HER2-negative breast cancer had more frequent alterations in GATA3, MDM2, CDK4, BRCA2 genes as compared with FBC patients of the same subtype." (PMID 39049124, 2024). "A positive feedback loop formed by ER and GATA3 is consistently present in ER+ breast cancer phenotypes, whereas in ER− breast cancer phenotypes, there exists a positive feedback loop on Notch and Slug." (PMID 39194502, 2024). "In breast cancer, decreased expression of FOXO1 has been linked to poor prognosis via interactions with the PI3K/Akt pathway, GATA3, and Annexin-1 expression." (PMID 39135158, 2024). "Depletion of GATA3 in MCF7 breast cancer cells reduces the expression of CtIP, an essential protein involved in HR, and impairs DNA damage response." (PMID 38627785, 2024). "We previously reported that GATA3 functions downstream of BRCA1 to suppress aberrant differentiation in breast cancer." (PMID 38627785, 2024). "For instance, while GATA3 is a highly sensitive marker for breast cancer, its expression in urothelial carcinomas and other tumors, such as parathyroid carcinoma, demands increased caution in its interpretation." (PMID 39518009, 2024). "Menin interacts with and promotes the expression of the transcription factors FOXA1 and GATA3 in ER-positive luminal breast cancer cells." (PMID 39336822, 2024). "Positive feedback loops formed by ER and GATA3, as well as by Slug and Notch, are essential for maintaining, respectively, the ER+ and ER- phenotypes of breast cancer." (PMID 39194502, 2024). "In this study, we discovered that depletion of Gata3, like that of Brca1, impairs DNA damage repair in breast cancer cells in vitro and in vivo." (PMID 38627785, 2024).
breast carcinoma (continued). "GATA3 has a high sensitivity, with expression reported in 90–95% of luminal breast cancers and a high percentage of triple-negative breast cancers (around 60–75%)." (PMID 39518009, 2024). "How GATA3 impacts DNA damage repair preventing aberrant cell differentiation in breast cancer remains elusive." (PMID 38627785, 2024). "We established a doxycycline-inducible GATA3 expression system in MDA-MB-231 mesenchymal breast cancer cells." (PMID 38281186, 2024). "Together, our data demonstrate that depletion of GATA3 impairs DNA damage response in mammary tumor cells in vitro and in mammary tumorigenesis in vivo." (PMID 38627785, 2024). "We transduced p18−/−;Brca1MGKO mammary tumor cells with pLVX-Flag or pLVX-Flag-Gata3 or transfected human MDA-MB231 cells with pBabe-Empty or pBabe-GATA3 and then treated them with ionizing radiation (IR) or VP16." (PMID 38627785, 2024). "We generated Gata3-overexpressing p18−/−;Brca1MGKO mammary tumor cells and transplanted them into the MFPs of mice." (PMID 38627785, 2024). "We found that in response to estrogen (17β-estradiol, E2) Gata3+/− and Brca1+/− mouse mammary tumor cells expressed higher levels of γH2AX than Gata3+/+;Brca1+/+ tumor cells." (PMID 38627785, 2024). "We then performed IHC for p18−/−;Gata3+/− mammary tumors and found that the expression of GATA3 was highly heterogeneous, some of the cells expressed GATA3, and some did not." (PMID 38627785, 2024). "We took advantage of mammary tumor cell lines derived from p18−/−;Brca1MGKO mice, in which both Brca1 and Gata3 were undetectable." (PMID 38627785, 2024). "We found that the treatment of Gata3+/− (p18−/−;Gata3+/−) mouse mammary tumor cells with VP16 led to significantly more γH2AX than the treatment of Gata3+/+;Brca1+/+ (MMTV-PyMT) tumor cells." (PMID 38627785, 2024). "In the present study, we discovered that spontaneously developed mammary tumors from p18−/−;Gata3+/− mice displayed a significantly increased number of cells with DNA DSBs when compared with the tumors from p18−/− mice." (PMID 38627785, 2024). "As a control, we conducted a similar treatment for Brca1+/− (p18−/−;Brca1+/−) mouse mammary tumor cells and also observed a significant increase of γH2AX in Brca1+/− cells relative to that in Gata3+/+;Brca1+/+ cells." (PMID 38627785, 2024). "With low cut-offs, such as any staining, more tumours turn out to be positive (e.g. primary breast carcinomas of mixed phenotype being positive in 94% (GATA3), 83% (GCDFP-15) and 89% (MGB)), but these become less frequent with higher cut-offs." (PMID 37012444, 2023). "For example, GATA3 acts as a downstream gene of BRCA1 to inhibit epithelial mesenchymal transition in breast cancer cells." (PMID 36468944, 2023). "Carcinomas with high GATA3 expression include basal cell carcinoma, breast cancer, germ cell tumors, and low-grade UC (>90 percent)." (PMID 37629741, 2023). "Conversely, GATA binding protein 3 (GATA3) is highly expressed in well-differentiated primary breast cancer." (PMID 37483522, 2023). "GATA-3 acts as a tumor suppressor in breast cancers of both transgenic mice and women, since it prevents the epithelial-to-mesenchymal transition induced by TGF-β and components of the TGF-pathway." (PMID 37483298, 2023). "The fact that GATA3 expression constituted a strong prognostic feature in our study was also in line with data from several recent studies which also suggested a strong link between reduced GATA3 expression and poor survival in breast cancer patients." (PMID 38137396, 2023). "Although our preliminary results suggest that GATA3 is a biomarker for DRFS in breast cancer patients following NAC treatment, there are limited applicable datasets with DRFS information of BC patients in the GEO database." (PMID 37900131, 2023).
breast carcinoma (continued). "Fascin-1 is responsible for invadopodia formation, migration and invasion of breast cancer cells, and it is a target of (TGFβ)-Smad4 signaling pathway which, in breast, has been found to be under the control of GATA-3." (PMID 37511011, 2023). "It was revealed that GATA-3 has a high positive predictive value (96.2 percent) for identifying the origin of malignant effusions due to breast cancer." (PMID 37383162, 2023). "GATA3 was considered as a breast cancer marker in CK7 + /CK20 − /ER − female adenocarcinomas, and other 2 early metastatic breast cancers were identified." (PMID 36346458, 2023). "Our results confirm that GATA3 and mammaglobin demonstrate expression predominantly in luminal breast cancers from African American women." (PMID 36747860, 2023). "Consistent with the findings derived from mouse models, we found that in human breast cancers, GATA3 expression is negatively correlated with FRA1 and positively correlated with c-FOS." (PMID 37353480, 2023). "GATA-3 was also shown to be an independent prognostic marker, with low expression predicting breast cancer recurrence." (PMID 38201547, 2023). "In breast cancer, the ductal and lobular carcinomas showed higher GATA3 expression rates (92% and 100%, respectively)." (PMID 37629741, 2023). "ER+ breast cancer cell lines depend specifically on transcription factors FOXA1 and GATA3, which are overexpressed in ER+ breast carcinomas." (PMID 36727483, 2023). "GATA binding protein 3 (GATA-3) is a differentiation marker related to differentiated states in breast cancer." (PMID 36996051, 2023). "SRY-related HMG-box 4 (SOX4) binding to the FBXW7 promoter upregulates FBXW7 expression in ER + breast cancers, causing enhanced turnover of GATA-binding protein 3 (GATA3), and thus promoting tamoxifen tolerance." (PMID 37658431, 2023). "GATA-3 has gained popularity as a sensitive marker for breast carcinoma in the breast cancer literature; nevertheless, it lacks specificity and should be used in concert with other markers." (PMID 37198611, 2023). "In conclusion, our meta-analysis results corroborated the findings from our bioinformatics analysis, indicating GATA3 as a protective factor against breast cancer recurrence." (PMID 37900131, 2023). "Common breast cancer mutations in the PIK3CA, GATA3 and KMT2C genes are significantly more prevalent in ER-positive/HER2-negative/low proliferation/luminal A cancers compared to the claudin-low group." (PMID 37345027, 2023). "GATA3 is often silenced by DNA methylation and its expression is lost or significantly reduced in BLBCs and metastasized breast cancers." (PMID 37353480, 2023). "The function of GATA3 in suppressing EMT and metastasis in breast cancers has been well studied in cell line models in which overexpression of GATA3 inhibits the expression of some of the EMT-TFs and enhances the expression of E-cad." (PMID 37353480, 2023). "In this study, we found that in both human and mouse breast cancers GATA3 and c-FOS are preferentially expressed in luminal-type mammary tumor cells, and are very low or absent in BLBCs." (PMID 37353480, 2023). "In this study, we explore how the extent of MI relates to GATA-3 expression, hormonal status, and the differentiation grade of breast cancer." (PMID 36996051, 2023). "Our results demonstrate three immune cell populations involved in breast cancer in relation to GATA3 expression, and the importance of this gene towards the immune microenvironment." (PMID 36836779, 2023).
breast carcinoma (continued). "The Supertarget genes, FOXA1, ESR1, and GATA3, are among the most studied prognostic markers and therapeutic targets in breast cancer." (PMID 37297004, 2023). "Corresponding to our observations, higher levels of GATA3 were also shown to be correlated with better survival in breast cancer patients." (PMID 38114659, 2023). "GATA3: GATA-binding protein 3 (GATA3) have unique clinical implications for breast cancer subtyping and classification." (PMID 37468832, 2023). "GATA-3 expression has been shown as a marker of good prognosis in human breast cancer and its higher expression was consistent with better rates of recurrence-free and overall survival." (PMID 37483298, 2023). "Mammaglobin and GATA-binding protein 3 are immunohistochemical biomarkers used to identify the origin of breast cancer." (PMID 37904355, 2023). "In human breast cancers, GATA3 expression is negatively correlated with FRA1 and positively correlated with c-FOS." (PMID 37353480, 2023). "The NF-κB/GATA3/STAT3 signaling pathway provided a promising target for overcoming DOX resistance in breast cancer." (PMID 37781691, 2023). "GATA3 has been proven to be affected in multiple breast cancer subtypes, such as its high expression in the Luminal A subtype due to its strong association with estrogen receptor expression." (PMID 36836779, 2023). "The histological findings of these tumors mimicked those of previous transverse colon tumors and breast cancers, with positivity for ER and GATA3 and negativity for E-cadherin." (PMID 37845365, 2023). "GATA3 is a transcription factor, and its expression in breast cancer strongly correlates with estrogen receptor (ER) expression." (PMID 36949070, 2023). "Immunohistochemically, the hyperexpression of T antigen, GATA-3 (a zinc-finger transcription factor specific for breast cancer), carbohydrate antigen 153 (specific biomarker for breast cancer), and β-catenin was noted." (PMID 37247123, 2023). "Notch3 maintains the epithelial phenotype of breast cancers through directly binding to the promoter and modifying the expression of ERα or GATA-3." (PMID 38124049, 2023). "Many of the associations that we found between the expression of AR and the expression of other prognostic and proliferation markers (GATA3 and Ki-67) are in keeping with what is known about the biology of breast carcinomas." (PMID 37345085, 2023). "Among these subtypes of breast cancer, the basal-like subtype is characterized by the low to absent expression of luminal differentiation markers including GATA3 and high enrichment for EMT markers." (PMID 37353480, 2023). "The histological morphology and immunohistochemistry showed some similarities with breast cancer, with tumor cells showing almost 100% expression of breast-related markers such as ER, PR, and GATA3." (PMID 38115331, 2023). "The results obtained in this study indicate a positive correlation between ER and GATA-3 expression in mammary tumors in dogs." (PMID 37483298, 2023). "Collectively, these results suggest that GATA-3 can be a relevant marker in the study of mammary tumor progression and has potential as a prognosis marker for predicting outcomes in canine mammary tumors." (PMID 37483298, 2023). "Scatter plot analysis revealed that the cut-off point (≥79.4%cells GATA-3 positive) highlighted statistically significant differences and defined the disease progression outcomes toward survival or death in dogs with mammary neoplasms." (PMID 37483298, 2023). "By correlating GATA-3 expression with survival in the cases of malignant mammary tumors, there was a directly proportional relationship and moderate and significant correlation (p = 0.0003; r = 0.6127)." (PMID 37483298, 2023).